POTED (POTE ankyrin domain family member D)
Synonyms: A26B3; ANKRD21; POTE; POTE-21; POTE21; CT104.1
Tractability: Antibody: UniProt places it where antibodies can reach, with high confidence; its Gene Ontology location is reachable by antibodies, with medium confidence. PROTAC: ubiquitination databases record sites on it.
Gene: Protein-coding gene on chromosome 21 (13,609,777 to 13,645,823, forward strand). Ensembl gene ENSG00000166351.
Subcellular location: Cell membrane
Gene Ontology:
Cellular component: plasma membrane
Genetic constraint (gnomAD): Loss-of-function variants: 3 observed, 6.55 expected, observed/expected ratio (o/e) 0.46, 90% interval 0.21 to 1.18. That is too few expected variants to judge how well the gene tolerates losing a copy. Missense variants: 25 observed, 87.14 expected, observed/expected ratio (o/e) 0.29, 90% interval 0.21 to 0.4. Synonymous variants: 6 observed, 24.69 expected, observed/expected ratio (o/e) 0.24, 90% interval 0.13 to 0.48.
Homologues: Paralogues in human: POTEB3 (95% identical), POTEB (89% identical), POTEB2 (89% identical), POTEC (89% identical), POTEI (86% identical), POTEF (85% identical), POTEE (85% identical), POTEJ (80% identical), POTEG (75% identical), POTEH (75% identical), POTEM (75% identical), POTEA (58% identical), and 2 more.
Diseases named in the same sentence as POTED in open-access papers:
POTED is named in the same sentence as 11 diseases in open-access papers, as found by Europe PMC text mining. Sharing a sentence is not in itself a finding about the gene and the disease. The quoted sentences say what the papers report.
triple-negative breast carcinoma (1 paper, 2022). An invasive breast carcinoma which is negative for expression of estrogen receptor (ER), progesterone receptor (PR), and human epidermal growth factor receptor 2 (HER2). "This gene is one of the 45 gene signatures for metastatic predictor in triple-negative breast cancer (TNBC) whereby the high expression of POTED was associated with poor prognosis." (PMID 36866106, 2022).
cancer (11 papers, 2011 to 2023). A tumor composed of atypical neoplastic, often pleomorphic cells that invade other tissues. "Nevertheless, the mechanism regulating the POTED expression in cancer remains to be elucidated." (PMID 36866106, 2022).
POTED also shares sentences with these, for which no sentence is quoted: tumor (3 papers); breast carcinoma (1); colorectal tumors (1); esophageal adenocarcinoma (1); melanoma (1); ovarian carcinoma (1); pancreatic cancers (1); prostate carcinoma (1); serous ovarian cancer (1).